UGT1A1 (UDP glucuronosyltransferase family 1 member A1)
Diseases named in the same sentence as UGT1A1 in open-access papers (continued):
Sharing a sentence is not in itself a finding about the gene and the disease.
breast carcinoma (continued). "The data suggest that genetic variation in SULT1A1 and UGT1A1 may influence breast cancer characteristics and might be important for breast cancer prognosis." (PMID 16280036, 2005). "We postulated that the decreased levels and lack of UGT1A1 mRNA in breast cancers might be due to a genetic variant in the promoter region of UGT1A1." (PMID 30349745, 2012). "For instance, a genetic variant in UGT1A1, which is characterized by the number of TA repeats in the TATA box of the promoter region, has been associated with reduced transcriptional activity towards estrogens in vitro and increased breast cancer risk in several population-based studies." (PMID 30349745, 2012). "Although not significant, UGT1A1 mRNA expression levels were still lower in breast cancer cases versus controls among AAs, (Tumor: 0.9 ± 0.8; Normal: 3.0 ± 1.7, p = 0.44)." (PMID 30349745, 2012). "We also demonstrated that UGT1A1 mRNA was slightly increased in Stage III and IV breast cancers." (PMID 30349745, 2012). "Although the number of specimens analyzed limited our study, we still observed a significant decrease in UGT1A1 mRNA levels among postmenopausal breast cancer cases versus controls and among EA women with breast cancer compared to EA without breast cancer." (PMID 30349745, 2012). "UGT1A1 mRNA levels were also significantly decreased in breast cancers as compared to normal breast tissues (Tumor: 0.5 ± 0.2; Normal: 4.1 ± 1.3, p = 0.0006)." (PMID 30349745, 2012). "Although the mean UGT1A1 mRNA expression was not significantly different among ethnic groups, UGT1A1 mRNA expression levels was lower in breast cancer cases vs controls among EAs (Tumor: 0.3 ± 0.1; Normal: 3.2 ± 1.5, p = 0.002)." (PMID 30349745, 2012). "Furthermore, although the splicing vector pSAD was initially developed to study the breast cancer genes BRCA1 and BRCA2, it has also been demonstrated to be a powerful tool to test other disease genes such as SERPINA1, CHD7, and UGT1A1, as well as others currently under investigation." (PMID 32211025, 2020). "Specifically, UGT1A1 and UGT1A4 were not expressed in 5 normal breast specimens and 40 and 39 breast cancers, respectively." (PMID 30349745, 2012).
metastatic colorectal cancer (22 papers, 2004 to 2026). "The study aimed to explore the correlation of UGT1A1 gene polymorphism of Guangxi Zhuang metastatic colorectal cancer (mCRC) with irinotecan -based chemotherapy, in order to develop an individualized irinotecan regimen for mCRC patients of Guangxi Zhuang." (PMID 32264830, 2020). "For example, cancer patients genetically predisposed with decreased UGT1A1 activity are at higher risk for severe toxicity when treated with anti-cancer agents such as irinotecan used in metastatic colorectal cancer." (PMID 32047295, 2020). "We examined the influence of the UGT1A1 gene promoter polymorphism in the toxicity profile, in the response rate and in the overall survival (OS) in 95 patients with metastatic colorectal cancer treated with an irinotecan-containing chemotherapy." (PMID 15280927, 2004). "In the present study, we examined the influence of uridine diphosphate glucuronosyl transferase UGT1A1 polymorphism on the toxicity profile, on the response rate and on the overall survival (OS) in patients with metastatic colorectal cancer treated with an irinotecan-containing chemotherapy." (PMID 15280927, 2004). "Patients with metastatic colorectal cancer (mCRC) had oncological benefits with irinotecan dose escalation of FOLFIRI regimen combined with bevacizumab according to UGT1A1 genotypes in our previous study." (PMID 35359363, 2022). "For example, irinotecan is widely used for the treatment of metastatic colorectal cancer and is metabolized by esterase to form a SN-38, which is further conjugated to UGT1A1." (PMID 30428922, 2018). "UGT1A1*28 genotype was determined in 218 patients receiving irinotecan (either first-line therapy with capecitabine or second-line as monotherapy) for metastatic colorectal cancer." (PMID 18594531, 2008). "However, the European Society for Medical Oncology recommends genotyping for this alteration in patients with metastatic colorectal cancer who will initiate CT with irinotecan, another agent that is also metabolized by the UGT1A1 pathway." (PMID 39518062, 2024). "In our study, we found the distribution frequencies of wild-type, heterozygous-type and homozygous-type UGT1A1 in Guangxi Zhuang patients of metastatic colorectal cancer differed from the reported distribution frequencies of genetic polymorphisms in European patients people and Chinese Han patients." (PMID 32264830, 2020). "Under the guidance of UGT1A1 genotype, some researchers explored the efficacy and safety of the regimen of regorafenib combined with increased-dose FOLFIRI for metastatic colorectal cancer patients." (PMID 35340156, 2022). "Currently, the clinically available pharmacogenetic markers for metastatic colorectal cancer (mCRC) are in genes related to drug metabolism, such as DPYD for fluoropyrimidines and UGT1A1 for irinotecan." (PMID 36432658, 2022). "A total of 132 metastatic colorectal cancer patients were genotyped for CYP3A4*1B, CYP3A4*18, CYP3A5*3, DPYD*2A, DPYD*5, DPYD c.1774C > T, UGT1A1*28, UGT1A1*6, ABCB1 c.1236C > T, ABCB1 c.3435C > T, ABCC2 c.3972C > T, and ABCG2 c.421C > A." (PMID 32778670, 2020). "UGT1A1*6 (211G>A), UGT1A1*28 (TA6>TA7), UGT1A1*60 (−3279T>G), UGT1A7 (387T>G), UGT1A7 (622T>C), and UGT1A9*1b (−118T9>T10, also named *22) were genotyped in 123 patients with metastatic colorectal cancer who had received irinotecan-based chemotherapy." (PMID 25175642, 2014). "UDP-glucuronosyltransferase 1A1 (UGT1A1) is a pivotal enzyme involved in metabolism of SN-38, the active metabolite of irinotecan commonly used to treat metastatic colorectal cancer." (PMID 20096102, 2010). "A recent study also revealed that neither UGT1A1*6 nor UGT1A1*28 affected treatment efficacy or progression-free survival in metastatic colorectal cancer." (PMID 41385496, 2025).
colon cancer (19 papers, 2010 to 2024). "The NCCN colon cancer guidelines advise caution and suggest alternative dosing strategies for UGT1A1 poor metabolizers (UGT1A*28 homozygous variants) scheduled to receive irinotecan; however, no testing guidelines have been established." (PMID 34572750, 2021). "Accordingly, positive UGT1A1 methylation in tumors, and subsequent repression of UGT1A1-associated metabolic pathways would be involved in retention of active SN-38 within colon cancer cells." (PMID 20096102, 2010). "Rapid phase II metabolism of belinostat via glucuronidation, primarily by the UGT1A1 enzyme, is the likely source of the short half-life of this drug, resulting in limited activity in solid tumors such as colon cancer." (PMID 37934338, 2024). "Luciferase assays sustained a role for USF1/2 and HNF1-alpha in UGT1A1 regulation in colon cancer cells." (PMID 20096102, 2010). "Loss of UGT1A1 methylation was further associated with an increase in UGT1A1 protein levels and with an enhanced SN-38 inactivation, by 300% in HCT116 colon cancer cells." (PMID 20096102, 2010). "To first investigate whether the differences between belinostat and Cubisbel IC50 concentrations was due to variable UGT1A1 expression in the three colon cancer cell lines, we quantified the protein concentration of this enzyme in each cell line." (PMID 37934338, 2024). "We investigated whether GTE directly alters the expression of UGT1A1 in the colon using human colon cancer-derived HT-29 cells." (PMID 37085597, 2023). "In addition, the higher the glucuronidation activity in colon cancer cells with low UGT1A1 methylation was, the higher was the inactivation of SN-38." (PMID 34034810, 2021). "Therefore, the combination of SFN and rapamycin appears to synergistically induce UGT1A1 gene expression in Caco-2 human colon cancer cells via the simultaneous stimulation of the Nrf2 and hPXR signaling pathways." (PMID 25364403, 2014). "In addition, human colon cancer cells has revealed that hypomethylation of the UGT1A1 5'-flanking sequence (-540 to -1) is important for UGT1A1 transcription." (PMID 20096102, 2010). "Considering that UGT1A1-mediated glucuronidation is the primary route of irinotecan inactivation, it was suggested that the level of UGT1A1 expression might contribute to the differential chemosensitivity of colon tumors." (PMID 20096102, 2010). "Interestingly a significant (r2 = 0.72, p < 0.001) correlation between PXR and UGT1A1 mRNA levels was found in human colon tumors." (PMID 20196838, 2010). "In contrast, aberrant hypermethylation of HNF1A downregulates the expression of UDP-glucuronosyltransferase 1A1 (UGT1A1), which remodels drug metabolism and transport pathways, locally inactivating anticancer drugs by glucuronidation in colon cancer cells." (PMID 37889117, 2023). "The UGT1A1 gene was picked up as one of the chemo-refractory signature genes in a genome-wide analysis, and UGT activation was observed in a colon cancer cell line which acquired resistance to CPT-11." (PMID 26482555, 2015). "More recently, another study demonstrated induction of UGT1A1 and UGT1A7 by irinotecan in colon cancer cells." (PMID 23110092, 2012). "In agreement with the presence of CpG islands in the HNF1A promoter, treatments of UGT1A1-negative HCT116 colon cancer cells with a DNA methyltransferase inhibitor restore HNF1A gene expression, as observed for UGT1A1." (PMID 20096102, 2010). "More specifically, the extent of UGT1A1 promoter methylation between CpG-1 (-4nt relative to the ATG) and -4 (-99nt relative to the ATG) of the promoter was shown to significantly predict UGT1A1 gene expression in colon cancer cell lines." (PMID 20096102, 2010).
Crigler-Najjar syndrome type 1 (17 papers, 2012 to 2025). Crigler-Najjar syndrome type 1 (CNS1) is the most severe form of CNS, a hereditary disorder of hepatic bilirubin conjugation, characterized by severe neonatal unconjugated hyperbilirubinemia due to a complete absence of hepatic bilirubin glucuronosyltransferase (BGT). "Crigler-Najjar syndrome type I (CN-I) is a rare autosomal recessive genetic disorder resulting from mutations in the UGT1A1 gene." (PMID 41523389, 2025). "The liposomal system containing the human uridinediphosphoglucuronate glucuronosyltransferase-1A1 gene (hUGT1A1) was administered through i.v. route into UGT1A1-deficient hyperbilirubinemic Gunn rats (model of Crigler-Najjar syndrome type 1)." (PMID 38587758, 2024). "Crigler Najjar Syndrome type I (CNSI) is a rare recessive disorder caused by mutations in the Ugt1a1 gene." (PMID 31965023, 2020). "The Crigler-Najjar Syndrome Type I (CNSI) is a rare genetic disorder caused by mutations in the Ugt1a1 gene." (PMID 25118822, 2014). "Crigler-Najjar Syndrome type I (CNI) is a rare deficiency of bilirubin UDP-glucuronosyl-transferase 1A1 (UGT1A1) activity caused by mutations of the UGT1A1 gene." (PMID 24223883, 2013). "Interestingly, type 1 Crigler-Najjar syndrome, a genetic deficiency in hepatic UGT1A1, is a metabolic disorder treated by hepatocyte transplantation." (PMID 26652177, 2015). "Secondly, treatment of Crigler–Najjar syndrome type 1 with an AAV8 vector expressing UDP-glucuronosyltransferase family 1-member A1 (UGT1A) showed normalization of total serum bilirubin levels in two animal models of the disease, Gunn rats and Ugt1a1-/- mice." (PMID 35740260, 2022). "Severe jaundice is also the hallmark of Crigler-Najjar syndrome type I (CNSI), in which mutations in the UGT1A1 gene result in the complete and life-long inactivity of the UGT1A1 enzyme." (PMID 25062689, 2014). "Gilbert’s syndrome and Crigler-Najjar syndrome Type I also share a similar genetic background: in both conditions, missense mutations affecting the coding region as well as promoter TATA box TA repeat variants that reduce UGT1A1 production were identified." (PMID 32796590, 2020).
gallstones (15 papers, 2013 to 2025). Solid crystalline precipitates in the biliary tract, usually formed in the gallbladder, resulting in the condition of cholelithiasis. "This study aimed to assess genotype and allele frequencies of common UGT1A1 variants in patients with gallstone and hepatitis B virus (HBV)-related hepatic failure." (PMID 36128448, 2022). "Genetic variation in UDP-glucuronosyltransferase 1A1 gene (UGT1A1) is a lithogenic risk factor for gallstone formation." (PMID 36128448, 2022). "The odds ratio of UGT1A1*27 was 25.22, showing that UGT1A1*27 increased the risk of gallstone in HBV-related hepatic failure." (PMID 36128448, 2022). "Based on the finding that UGT1A1*27 and UGT1A1*28 variants were significantly observed in gallstone-related liver failure induced by HBV, our project highlights the value of UGT1A1 genotypes in genetic testing and pathogenetic studies." (PMID 36128448, 2022). "The aim of this study was to analyze the association between UGT1A1 polymorphisms (UGT1A1*6, UGT1A1*27, UGT1A1*28, and UGT1A1*6) and gallstone in patients with hepatitis B-related liver failure." (PMID 36128448, 2022). "Although this study first reports the effects of UGT1A1 single-nucleotide polymorphism on gallstone-related liver failure caused by HBV, these results should be seriously viewed because of the small sample size, or be confirmed by in vivo experiments." (PMID 36128448, 2022). "In total, this study broadens the knowledge concerning the association between gallstone and UGT1A1 variations in patients with HBV-related liver failure." (PMID 36128448, 2022). "Jaundice and a predisposition to gallstones are associated with a polymorphic variant in the promoter of the UGT1A1 gene." (PMID 34766559, 2021). "(TA) n repeat sequence (rs8175347) of UGT1A1 gene promoter polymorphism is associated with serum bilirubin levels and gallstones among different sickle cell anaemia (SCA) populations." (PMID 31619193, 2019). "Genetic studies exploring polymorphisms in UGT1A1 and related genes could further clarify their role in gallstone susceptibility, paving the way for personalized management strategies." (PMID 41356983, 2025). "For instance, variations in genes associated with bilirubin metabolism, such as UGT1A1, may exacerbate the risk of gallstone formation." (PMID 41356983, 2025). "Based on the results of the present study showing high frequency of UGT1A1 variant with low enzymatic activity, we infer that genotyping of UGT1A1 polymorphism might help to predict the development of gallstones in HS." (PMID 31122244, 2019). "Variants of the gene encoding UGT1A1 (uridine 5’-diphosphate (UDP)- glucuronosyltransferase 1A1) responsible for bilirubin conjugation were correlated with the risk of gallstones and stone bilirubin content, suggesting common factors in the pathogenesis of cholesterol and pigment gallstones." (PMID 30794560, 2019). "However, the effect of UGT1A1*6 gene polymorphisms on gallstone in patients with HBV-related liver failure is still unknown." (PMID 36128448, 2022). "This study shows that children with co-inheritance of low UGT1A1 (TA) n affinity genotypes may be at risk of gallstone, thus highlighting the need to closely follow them up for early identification of possible gallstone complications and provision of appropriate intervention(s)." (PMID 31619193, 2019). "Despite these, it was able to confirm that UGT1A1 (TA) n genotypes are tightly associated with bilirubin and LDH levels, and the development of gallstones among young Nigerians with SCA." (PMID 31619193, 2019). "In addition to the TA7/7 genotype, other authors, have reported that some other low-activity UGT1A1 (TA) n genotypes like TA7/8 and TA8/8 predispose SCA patients to gallstones as found in this study." (PMID 31619193, 2019).
gallstones (continued). "Furthermore, when those with gallstones were compared with age- and sex-matched patients within the same UGT1A1 (TA) n genotype subgroup, only serum bilirubin and HbF showed significant differences between the two groups." (PMID 31619193, 2019). "Our finding that the low-activity UGT1A1 (TA) n genotype was associated with gallstones confirms previous observations that SCA patients with the low-activity UGT1A1 (TA) n genotypes especially the TA7/7, are at risk of developing gallstones." (PMID 31619193, 2019). "Although, bilirubin and fetal hemoglobin (HbF) of patients with gallstones were significantly different from those without gallstone, only the serum bilirubin was associated with UGT1A1 (TA) n genotypes on multivariate analysis (p < 0.0001)." (PMID 31619193, 2019). "This may imply that gallstone and hepatic failure are related to UGT1A1*27." (PMID 36128448, 2022). "However, the information is lacking about the important UGT1A1 gene variations in gallstone-related liver failure caused by HBV infection." (PMID 36128448, 2022). "In addition, it also suggests that the pathway to elevated serum bilirubin and gallstone development, among our study cohort, may not be exclusively driven by hemolysis but also by UGT1A1 polymorphisms." (PMID 31619193, 2019).
lung carcinoma (14 papers, 2012 to 2023). "Studies show that genetic polymorphisms in genes that encode enzymes involved in the metabolism of tobacco carcinogens, such as UGT1A1, can affect the individual risk of lung cancer." (PMID 35328047, 2022). "The aim of this study was to investigate possible associations between UGT1A1 gene polymorphism (rs8175347) and lung cancer risk in an Amazonian population." (PMID 35328047, 2022). "Our objective was to investigate associations between a UGT1A1 gene polymorphism (rs8175347) and lung cancer risk in an Amazonian population." (PMID 35328047, 2022). "Overall, we did not observe an association between bilirubin levels predicted by either the UGT1A1 SNP or the non-UGT1A1 SNPs and lung cancer risk (OR per 1-SD 0.98; 95% CI 0.94–1.02, by UGT1A1 SNP; and OR 0.91; 95% CI 0.83–1.00, by non-UGT1A1 SNPs)." (PMID 33671849, 2021). "In addition to the susceptibility to the development of lung cancer, studies regarding polymorphism in the UGT1A1 gene (rs8175347) have identified its association with the response to chemotherapy with irinotecan." (PMID 35328047, 2022). "A total of 286 blood specimens from the lung cancer patients who were hospitalized in Guangdong General Hospital between April 2014 to May 2015 were detected UGT1A1*28 polymorphism by fragment analysis method." (PMID 29277179, 2017). "The reduced enzymatic action of UGT1A1, due to the TA7 variant, may be associated with severe toxicities in patients receiving irinotecan, including patients with lung cancer." (PMID 35328047, 2022). "Elevated expression of UGT1A1 and UGT1A10 enhances metabolism of SN-38, resulting in a reduced concentration of SN-38 in the lung cancer cells." (PMID 35002522, 2022). "The authors of that manuscript also demonstrated that the increased levels of UGT1A1 and UGT1A10 increased resistance of lung cancer cells to irinotecan." (PMID 23110092, 2012). "At this time, we are not aware of any other large-scale prospective studies of UGT1A1 variation and lung cancer specifically." (PMID 32855344, 2020).